CASP10 (caspase 10)
Description:
Involved in the activation cascade of caspases responsible for apoptosis execution. Recruited to both Fas- and TNFR-1 receptors in a FADD dependent manner. May participate in the granzyme B apoptotic pathways. Cleaves and activates effector caspases CASP3, CASP4, CASP6, CASP7, CASP8 and CASP9. Hydrolyzes the small-molecule substrates, Tyr-Val-Ala-Asp-|-AMC and Asp-Glu-Val-Asp-|-AMC. Isoform 7 can enhance NF-kappaB activity but promotes only slight apoptosis. Isoform C is proteolytically inactive.
Synonyms: FLICE2; MCH4; FLICE-2; ALPS2
Tractability: Small molecule: a drug acting on it is in phase 2 or 3 trials; a high-quality ligand is known. PROTAC: ubiquitination databases record sites on it; its protein half-life has been measured; a small molecule that binds it is known.
Target class: Cysteine protease; Protease; Cysteine protease CD clan; Enzyme; Cysteine protease C14 family
Gene: Protein-coding gene on chromosome 2 (201,182,693 to 201,229,428, forward strand). Ensembl gene ENSG00000003400.
Subcellular location (Human Protein Atlas): Golgi apparatus; Vesicles
Pathways (Reactome):
Signal Transduction: FasL/ CD95L signaling; TRAIL signaling
Immune System: NF-kB activation through FADD/RIP-1 pathway mediated by caspase-8 and -10
Gene Ontology:
Molecular function: cysteine-type endopeptidase activity; death effector domain binding; protein binding; ubiquitin protein ligase binding; cysteine-type peptidase activity
Biological process: positive regulation of canonical NF-kappaB signal transduction; positive regulation of execution phase of apoptosis; protein maturation; apoptotic process; positive regulation of neuron apoptotic process; proteolysis; regulation of apoptotic process
Cellular component: CD95 death-inducing signaling complex; ripoptosome; cytoplasm; cytosol
Genetic constraint (gnomAD): Loss-of-function variants: 31 observed, 39.98 expected, observed/expected ratio (o/e) 0.78, 90% interval 0.58 to 1.05. The upper end of that interval is the gene's LOEUF score, 1.05, which puts it in group 4 of 6, group 1 being the genes least tolerant of losing a copy. Missense variants: 545 observed, 585.66 expected, observed/expected ratio (o/e) 0.93, 90% interval 0.87 to 1. Synonymous variants: 212 observed, 232.17 expected, observed/expected ratio (o/e) 0.91, 90% interval 0.82 to 1.02.
Gene-disease validity (ClinGen):
ClinGen rates the evidence that CASP10 causes each of these diseases.
autoimmune lymphoproliferative syndrome type 2A (autosomal dominant): Limited. A rare, primary immunodeficiency with an autosomal dominant pattern of inheritance but incomplete penetrance.
Homologues: Orthologues: chimpanzee CASP10 (90% identical), macaque CASP10 (89% identical), pig CASP10 (67% identical), dog CASP10 (66% identical), rabbit CASP10 (62% identical), guinea pig CASP10 (56% identical), tropical clawed frog casp10 (40% identical), zebrafish casp10 (32% identical), Drosophila melanogaster Dredd (22% identical), Caenorhabditis elegans ced-3 (20% identical), Caenorhabditis elegans csp-2 (18% identical), Caenorhabditis elegans csp-1 (17% identical), and 1 more. Paralogues in human: CASP8 (34% identical), CFLAR (21% identical), CASP9 (20% identical), CASP2 (20% identical), CASP7 (19% identical), CASP6 (18% identical), CASP3 (16% identical), CASP1 (15% identical), CASP5 (15% identical), CASP12 (13% identical), CASP4 (13% identical), CASP14 (13% identical), and 4 more.
Diseases named in the same sentence as CASP10 in open-access papers:
CASP10 is named in the same sentence as 55 diseases in open-access papers, as found by Europe PMC text mining. Sharing a sentence is not in itself a finding about the gene and the disease. The quoted sentences say what the papers report.
autoimmune lymphoproliferative syndrome (16 papers, 2007 to 2025). Autoimmune lymphoproliferative syndrome (ALPS) is a rare, inherited disorder characterized by non-malignant lymphoproliferation, multilineage cytopenias, and a lifelong increased risk of Hodgkin's and non-Hodgkin's lymphoma. "It has been shown that hereditary CASP10 gene mutation is a condition for lymphocyte defects and dendritic cell apoptosis in the autoimmune lymphoproliferative syndrome ALPS." (PMID 40566633, 2025). "CASP10 is a causative gene for autoimmune lymphoproliferative syndrome (ALPS) type IIa, and its mutation hot spot is the protease domain (CASc) with missense mutation." (PMID 33903686, 2021). "In addition, the mutation of the CASP10 gene is one of the causes of type IIA autoimmune lymphoproliferative syndrome (ALPS)." (PMID 40566633, 2025). "Patients with autoimmune lymphoproliferative syndrome (ALPS), who bear mutations affecting FasL or caspase-10, show increased risk of Hodgkin (HL) and non-Hodgkin lymphoma (NHL), highlighting the importance of the extrinsic apoptosis pathway." (PMID 32466293, 2020). "Autoimmune lymphoproliferative syndrome (ALPS) is a group of disorders primarily due to impaired lymphocyte apoptosis, whose typical forms are caused by defects in the FAS pathway (FAS, FASLG, and CASP10)." (PMID 35601409, 2022). "Autoimmune lymphoproliferative syndrome (ALPS), characterized by chronic lymphoproliferation, autoimmune manifestations, and an increased lymphoma risk, stems from defects in lymphocyte apoptosis, particularly in components of the apoptotic pathway (e.g., FAS, FASL, FADD, CASP10, and CASP8)." (PMID 38535602, 2024). "Furthermore, patients with autoimmune lymphoproliferative syndrome (ALPS) have been shown to carry somatic or germline mutations in the genes that encode FAS, Fas-ligand, caspase 10, caspase 8, NRAS, and KRAS." (PMID 32121251, 2020). "The Mendelian disease autoimmune lymphoproliferative syndrome (ALPS) arises from defects in the genes FAS, CASP8, and CASP10, which coordinate the Fas-dependent apoptosis that is critical for thymocyte development." (PMID 38589365, 2024).
breast carcinoma (8 papers, 2010 to 2025). "CASP10 is more highly expressed in normal tissue compared to tumor tissue, and higher expression is associated with better prognosis for breast cancer." (PMID 38965614, 2024). "Consistently, CASP10 is frequently downregulated in breast cancer, and overexpression of CASP10 appeares to improve the overall prognosis in breast cancer, which indicates a better prognosis if being treated by Enz." (PMID 38965614, 2024). "This solution was also enriched in genes known to be associated with breast cancer susceptibility (BLM, CASP8, CASP10, DNAJC1, FGFR2, MRPS30, and SLC4A7, P-value = 3 × 10−4)." (PMID 33735170, 2021). "miR-421 was found to be upregulated in breast cancer tissues and inhibits apoptosis by inhibiting caspase-10 expression." (PMID 31857500, 2019). "In addition to breast cancer, Caspase 10 is also associated with basal cell carcinoma, non-melanoma skin carcinoma, non-small cell lung carcinoma, prostate carcinoma, and cancer risk in general." (PMID 38965614, 2024). "For caspase 10, an approximately 1.5-fold increase in its activity was observed after exposure to 1.5 μM EDA-71 compared with the control in both breast cancer cell lines." (PMID 36077839, 2022). "At the higher concentration (3 μM) of the tested compound, an over 7-fold (10.0 ± 0.5%) in MCF-7 breast cancer cells and an approximately 3-fold (15.5 ± 2.7%) in MDA-MB-231 triple-negative breast cancer cells increase in caspase 10 activity compared with the control was reported." (PMID 36077839, 2022). "To investigate the role of caspase-10 in the apoptosis pathway induced by knockdown of CAAP, we utilized MCF-7 breast cancer cells that express neither caspase-3 nor caspase-10." (PMID 21980415, 2011). "TRAIL, TRAILR1, TRAF4, CASP10, and APAF1 increase upon Sin3A knockdown in MCF7, but not MDA-MB-231, breast cancer cells." (PMID 20920219, 2010).
multiple myeloma (8 papers, 2014 to 2023). "We also addressed involvement of caspase-10 in controlling autophagy, as previously shown in multiple myeloma." (PMID 37841311, 2023). "In several multiple myeloma cell lines, caspase 10 catalytic activity and cFLIPL expression, driven by IRF4, are required for cell viability irrespective of genetic abnormalities." (PMID 32591647, 2020). "In line with our data and a more complex role of caspase-10, a recent study has proposed a pro-survival function of endogenous caspase-10, as it was shown to inhibit autophagic cell death in multiple myeloma cell lines." (PMID 28445729, 2017). "Autophagic cell death regulated by caspase 10 has also been reported in multiple myeloma and acute Ras overexpression can lead to autophagic cell death." (PMID 26248051, 2015). "Previous studies have shown that these anti-myeloma agents induced apoptosis through activating caspase-3 and -8 in MM cells, while caspase-10 was shown to play pivotal roles in maintaining MM cell survival by balancing the pro-survival and pro-death effects of autophagy." (PMID 35965541, 2022). "Consequently, preventing caspase-10 cleavage promotes myeloma cell survival." (PMID 25605012, 2015). "In brief, human myeloma lines depend for their survival on IRF4, which, through a caspase 10-dependent mechanism, prevents excessive autophagy from executing non-apoptotic myeloma cell death." (PMID 24659989, 2014). "Caspase 10 inhibition by a broad-spectrum caspase inhibitor, Q-VD-OPH or a more selective caspase 10 inhibitor kills myeloma cells without the hallmarks of apoptosis but through the induction of ACD." (PMID 32591647, 2020).
melanoma (4 papers, 2009 to 2024). A malignant, usually aggressive tumor composed of atypical, neoplastic melanocytes. "Functional polymorphisms in CASP8 and CASP10 may also influence melanoma susceptibility." (PMID 39329914, 2024). "As observed in HeLa cells, SK-Mel melanoma showed a significant sensitivity to CD95L after the depletion of caspase-10." (PMID 28445729, 2017). "The inhibition of caspase-8 or caspase-10 (as well as disabling caspase-8) significantly reduces the efficacy of treatment, suggesting that this downstream pathway may play an important role in the response of melanoma cells to combination therapy." (PMID 39329914, 2024). "Inhibition of either caspase-8 or caspase-10 (as well as caspase-8 knockdown) significantly reduces treatment efficacy suggesting that this downstream pathway may play an important role in the response of melanoma cells to the combination treatment." (PMID 19684859, 2009). "Next, we investigated other cell lines (diverse melanoma lines [SK-Mel, IGR, WK, and MC], B cell and T cell lymphoma [BJAB and Jurkat], and spontaneously transformed keratinocytes [HaCaT]) for the impact of caspase-10 on CD95L-induced cell death." (PMID 28445729, 2017).
gastric cancer (3 papers, 2010 to 2023). A primary or metastatic malignant neoplasm involving the stomach. "In a different study, however, the majority of gastric cancers displayed enhanced expression of caspase-10 when compared to normal mucosa." (PMID 24281211, 2010). "Therefore, impairment of caspase-10 function is not very likely to be of relevance for gastric cancer." (PMID 24281211, 2010).
Immunodeficiency (3 papers, 2019 to 2025). Failure of the immune system to protect the body adequately from infection, due to the absence or insufficiency of some component process or substance. "Moreover, caspase-8 deficiency is associated with defects in B and T cell activation and immunodeficiency whereas caspase-10 deficiency is associated with susceptibility to infections and arthritis, pointing to a dual role of caspases in inducing both apoptotic and non-apoptotic signaling." (PMID 31114586, 2019). "Disorder of the immune system and the abnormality of dendritic cells are related to the dysfunction of CASP10." (PMID 40566633, 2025). "It is speculated that the dysfunction of caspase-10 can seriously affect the immune regulatory system of the body, resulting in a series of immune diseases." (PMID 40566633, 2025). "It is speculated that the down-regulation of CASP10 expression in the absence of disease is normal, while the down-regulation of CASP10 expression in the disease may be one of the processes or results of the immune system disorder caused by COVID-19 infection." (PMID 40566633, 2025).
leukemia (3 papers, 2010 to 2025). A malignant (clonal) hematologic disorder, involving hematopoietic stem cells and characterized by the presence of primitive or atypical myeloid or lymphoid cells in the bone marrow and the blood. "The present study shows that FasL-induced cell death was completely impaired in caspase-8- and caspase-10-doubly deficient (I9-2e) Jurkat leukaemia T-cell lines." (PMID 21049020, 2010). "However, the association between exonic deletion of CASP10 and leukemia in our patient is unclear in this study." (PMID 33903686, 2021).
lung carcinoma (3 papers, 2019 to 2022). "Frequent FADD and caspase-10 mutations have also been reported in lung cancer, playing a role in the development of lymph node metastasis." (PMID 32847023, 2020). "We next examined the effect of caspase-10 on ACLY promoted tumor malignancy in orthotopic lung cancer model." (PMID 31534141, 2019). "In the previous study, the downregulated genes CASP10 and CD177 and the upregulated genes BAK1, ST14, CD82, and MUC4 were detected as biomarkers for lung cancer by the joint sparse regression model." (PMID 35923697, 2022). "Thus our data suggests that dysregulation of caspase-10 expression and consequent upregulation of ACLY is critical for lung cancer progression." (PMID 31534141, 2019).
primary biliary cholangitis (3 papers, 2025). Primary biliary cholangitis (PBC) is a chronic and slowly progressive cholestatic liver disease of autoimmune etiology characterized by injury of the intrahepatic bile ducts that may eventually lead to liver failure. "Studies have shown that in the autoimmune disease primary biliary cholangitis (PBC), dysfunction of caspase-10 may lead to cell death and dysregulation of inflammatory response, and the dysregulation of inflammatory response may participate in the pathogenesis of PBC." (PMID 40566633, 2025).
prostate carcinoma (3 papers, 2017 to 2024). A carcinoma that arises from epithelial cells of the prostate gland. "We also newly showed that caspase-10 was dispensable for platinum drug-mediated stimulation of TRAIL-induced apoptosis in prostate cancer cells." (PMID 29182622, 2017). "We showed that potentiation of cell death in cisplatin/LA-12 and TRAIL-treated prostate cancer cell lines was accompanied by enhanced processing of caspase-10." (PMID 29182622, 2017). "An apparent enhancement of caspase-10 cleavage in cisplatin/LA-12 and TRAIL-treated prostate cancer cells prompted us to investigate in more detail its possible involvement in the cooperative cytotoxic action of the drugs." (PMID 29182622, 2017). "In present study, we newly showed that caspase-10 was dispensable for realization of the cytotoxic potential of the cisplatin/LA-12 and TRAIL combination in prostate cancer cells, and also did not significantly affect the drug-induced Bid cleavage." (PMID 29182622, 2017).
viral infection (3 papers, 2014 to 2023). "While the majority caspases were activated by the viral infection, caspase 10, the most transcriptionally upregulated isoform, exhibited the most functional activation in infected (p24+) compared to p24- or uninfected populations." (PMID 36780482, 2023). "In this study, the expression levels of the majority of genes involved in the TNF signaling pathway, including those encoding TNF, IL-6, CCL20, caspase 10, caspase 3, NF-κB, and TGF-β-activated kinase 1 (TAK1), were significantly downregulated after viral infection." (PMID 25423176, 2014).
clubfoot (2 papers, 2024 to 2025). The most common congenital deformation of the foot, occurring in 1 of 1,000 live births. "Initially, genes associatedwith clubfoot (PITX1, TBX4, HOXA9, HOXD10, HOXD12,HOXD13, HOXA9, TPM1, TPM2, COL9A1, FLNB, CASP8,CASP10, UTX, CHD1, RIPPLY2, CAND2, WNT7) werescreened for potential variants." (PMID 38952703, 2024). "Further genotyping of 40 SNPs in seven apoptosis-related genes, including CASP10, in 210 simplex trios and 139 multiplex families has confirmed that variations within these genes may play a role in the development of clubfoot." (PMID 40746736, 2025). "Furthermore, an SNP within the HOXA9 gene in conjunction with CASP10 has implications in apoptosis among simplex clubfoot cases." (PMID 40746736, 2025).
colorectal cancer (2 papers, 2021 to 2024). A primary or metastatic malignant neoplasm that affects the colon or rectum. "The activity level of the apoptosis-associated markers (CASP9 and CASP10) may help assess the prognosis for patients with stage II colorectal cancer." (PMID 38674831, 2024). "Microarray profiles show that parental and oxaliplatin-resistant (OxR) colorectal cancer (CRC) cell lines have similar expression of apoptotic transcripts while OxR derivatives have significantly downregulated CASP10." (PMID 34342264, 2021).
glioblastoma (2 papers, 2017 to 2020). The most malignant astrocytic tumor (WHO grade IV).
Obesity (2 papers, 2019 to 2020). Accumulation of substantial excess body fat. "This suggests that both genetic and epigenetic modifications of the CASP10 gene may have an important translation implication in diabetes and cancer, which are common comorbid conditions associated with obesity." (PMID 31092860, 2019). "In addition, in this analysis, a few other regions emerged: a large region on SSC6 that encompasses the AGBL4 gene, which is involved in obesity and fat deposition traits, and a few other regions on SSC15, including a region close to the previously reported CASP10 gene." (PMID 32591011, 2020).
common variable immunodeficiency (1 paper, 2022). "Finally, ALPS or ALPS-like features may also arise from the complementary effect of variants in CASP10 and in another non-FAS gene, such as CASP8 or TNFRSF13C (i.e., BAFF receptor, whose mutations are typically associated with common variable immunodeficiency, CVID)." (PMID 35059842, 2022).
COVID-19 (1 paper, 2025). A disease caused by infection with severe acute respiratory syndrome coronavirus 2. "However, direct evidence for a specific link between COVID-19 and CASP10 is still lacking." (PMID 40566633, 2025).
ependymoma (1 paper, 2016). A WHO grade II, slow growing tumor of children and young adults, usually located intraventricularly. "Poor prognostic features were found in two other patients: low expression of PAX8, FHIT, CASP10, CHD2, with high expression of CHD11, FUS, and MTA1 in a patient with Ewing sarcoma, and gain of 1q and loss of 6q and overexpression of TNC, CALB1, PLAG1, ALDH1L1, and RELN in a patient with ependymoma." (PMID 28007021, 2016).
follicular adenomas (1 paper, 2009). "In all cases except one (CASP10, F-test, p<0.05), the gene expression level differentiated not only between macro- and micro-follicular adenomas but also between follicular adenomas and oncocytic adenomas, as in the case of CDH16 and CRABP1 genes." (PMID 19893615, 2009).
gastritis (1 paper, 2023). Inflammation of the stomach. "In this study, we screened 11 important lncRNAs (AFAP1-AS1, MIR155HG, LINC00472, and FAM201A) and mRNAs (CASP10, SLC26A2, TRIB1, BMP2K, SCAMP1, TNKS1BP1, and MBOAT2) according to the gene expression profiles of gastric epithelial tissues in different stages of Hp infection-induced gastritis." (PMID 37249580, 2023).
hepatocellular carcinoma (1 paper, 2025). A malignant tumor that arises from hepatocytes. "In a study of hepatocellular carcinoma in rats, caspase-10 was significantly increased in the positively treated group compared to the positive control group and resulted in a decrease in tumor incidence and tumor size." (PMID 40566633, 2025).